FPR2 (formyl peptide receptor 2)
Diseases named in the same sentence as FPR2 in open-access papers (continued):
Sharing a sentence is not in itself a finding about the gene and the disease.
infection (continued). "In mice, formylated peptide receptors Fpr1 and Fpr2 detect formylated peptides produced by Lm and are required for neutrophil chemotaxis to the site of infection and ultimately Lm clearance." (PMID 37706879, 2023). "FPR2 is crucial for the recruitment of neutrophils to the sites of infection, and it can influence inflammation." (PMID 37325619, 2023). "Higher level of NETs was also found in the plasma and PLF of Fpr2-/- mice at 6 h post-infection, which was further confirmed by immunofluorescence results." (PMID 36776849, 2023). "WRW4 and BOC2 are commercially available antagonists of FPR2 that were tested in vivo during IAV infection and shown to protect mice from lethality associated to infection." (PMID 37190040, 2023). "The increased expression of Fpr2 gene in the spleen implied a participatory role of Fpr2 during infection." (PMID 36776849, 2023). "We focused on leukocyte activity during infection to understand the role of Fpr2 in the STSLS-induced inflammatory response." (PMID 36776849, 2023). "When compared with the current study on the STSLS model, both studies revealed an anti-recruitment function of Fpr2 during infection, but opposite effects on disease development in the different infection models." (PMID 36776849, 2023). "Plasma levels of mast cell protease 1 (MCPT-1) and CCL2 were increased in either AnxA1 and FPR2 KO animals compared to their respective controls after infection." (PMID 35293862, 2022). "High concentrations of formyl peptides activate formyl peptide receptor 2 (FPR2) and induce neutrophil diapedesis at infection sites." (PMID 36483296, 2022). "The peripheral blood of mice was added to GBS in the mid-log phase to induce infection, and the results demonstrated that the killing ability of Fpr2-knockout mice was weakened." (PMID 34899755, 2021). "Compared to monocytes/macrophages, B cells, and T cells, the recruitment of neutrophils in Fpr2-/- mice significantly blunted in early stages 3 and 6 h after the infection." (PMID 34899755, 2021). "The effects of Fpr2-/- mice on host anti-infection has been studied in S. pneumoniae, S. aureus, S. suis, L. monocytogenes, and E. coli." (PMID 34899755, 2021). "Preventing PSM degradation during infection represents an important survival strategy to ensure FPR2 activation." (PMID 34552584, 2021). "Data above suggested that the over-sensitivity to GBS infections seen in Fpr2-/-mice is related to its reduced ability to recruit neutrophils to the infection site." (PMID 34899755, 2021). "Our results demonstrated that Fpr2 deletion significantly down-regulated the Saa3 expression, which is an important inflammation-related factor during the acute infection phase." (PMID 34899755, 2021). "Our results demonstrated that 48 h after infection, the survival rate of mice in the Fpr2-/- group decreased significantly, to less than 50%." (PMID 34899755, 2021). "FPR2 antagonist treatment reverses the effect of LXA4/FPR2 by inducing leukocyte migration into the infection site and increasing bacterial killing." (PMID 33082511, 2020). "The present work supports a model in which FPR2/Fpr2 governs epithelial defenses against infection, including the mucus layer, and restitution of damaged mucosal surfaces." (PMID 31234710, 2019). "We found that, upon infection and cell treatment with the specific FPR2 antagonist WRW4 or the anti-FPR2 monoclonal antibody, FN-1D6-AI, influenza viruses were blocked into endosomes." (PMID 29738458, 2018). "Our approach to reducing excessive inflammation in co-infected mice was to therapeutically deliver exogenous AT-RvD1 during the acute phase of infection, where FPR2/ALX is the only characterized receptor for AT-RvD1 in mice." (PMID 30459754, 2018). "Conversely, experiments using FPR2 antagonists in a preclinical model of IAV infections in mice showed that blocking FPR2 protects animals from lethal infections." (PMID 28928730, 2017).
infection (continued). "In this case, FPR2 would turn pro-inflammatory, by binding at later stages of infection to pro-inflammatory ligands." (PMID 28928730, 2017). "Another possibility is that the initial protective host response to infection required to eliminate the virus is impaired because FPR2 is inadequately activated after infection by IAV-expressing Annexin A1." (PMID 28928730, 2017). "On the one hand, it has been demonstrated that neutrophils are necessary to control the infection; to subvert neutrophil attraction through FPR2 S." (PMID 22457627, 2012). "Intriguingly, Fpr2 deletion (Fpr2−/−) did not impact weight loss or bacterial growth as infection in these animals led to comparable body weight and CFUs in the lung as Wt." (PMID 38853986, 2024). "Collectively, these studies suggest that the AnxA1/FPR2 axis could be a potential target for host-directed therapies for arbovirus-induced infections, such as CHIKV, DENV, and ZIKV, due to its protective role in these diseases." (PMID 37190040, 2023). "Following infection with E. coli O22:H8, the expression of Fpr2 in colon epithelial cells was upregulated, and the products derived from E. coli O22:H8 induced migration and proliferation of colon epithelial cells through Fpr2." (PMID 37322488, 2023). "Fpr2-/- mice have been used in many studies focused on infection or inflammation." (PMID 36776849, 2023). "Infection with E. coli O22:H8 stimulated the upregulation of Fpr2 expression, and its products induced the migration and proliferation of colon epithelial cells through Fpr2." (PMID 37322488, 2023). "The infection induced significant Fpr2 transcription in the brain after 6 and 18 h." (PMID 33318141, 2021). "Here, We clarified that Fpr2, as a chemotactic receptor, could not only directly chemotactic neutrophils, but also regulate the production of chemokines to control infection by chemotactic neutrophils." (PMID 34899755, 2021). "A recent study demonstrated an important role of Fpr2 in orchestrating the protection of colon mucosa from infection by Citrobacter (C) rodentium, which is an attaching and “effacing” intestinal mouse pathogen that shares similar virulent patterns with human enteropathogenic E. coli." (PMID 32038501, 2020). "Thus, PM2 constitutes the first FPR2 antagonist displaying cross-species selectivity and potency, and thus can be considered to be a convenient tool for elucidating the specific regulatory roles of FPR2 via mouse models of infection and inflammation." (PMID 32983167, 2020). "The contribution of FPR2 to wound healing and anti-inflammatory effect may explain why WT mice recover faster from the infection-induced tissue injury than Fpr2−/− mice as evident at day 19 PI in the current study." (PMID 31234710, 2019). "Thus, Fpr2 contributes to protection against infection and influence mucus production, secretion and organization." (PMID 31234710, 2019). "Enhancing the activity of FPR2 by selective agonists may have therapeutic benefits to protect against infection or aid mucosal healing; however, further studies are needed to support this." (PMID 31234710, 2019). "Similarly, CXCL1 and CXCL2 quickly increased in the early stages of GBS infection, while a significant difference in these two factors in WT and Fpr2-/- can be detected at 1 hour and 3 hours for both i.v. and i.p. infection route, which is consistent with that of the neutrophils increase." (PMID 34899755, 2021). "In addition, Fpr2 KO mice showed a higher C. rodentium load in the spleen after infection and there was an enhanced translocation of C. rodentium and E. coli across an artificial mucosal surface to the basolateral compartment established in vitro, in the absence of functional Fpr2." (PMID 32038501, 2020). "In addition, FPR2 antagonists will most likely generate a long lasting protection since it tempers inflammation which is responsible for tissue injury at later stages of the infection." (PMID 28928730, 2017).
infection (continued). "FPR2 blockade with WRW4 similarly inhibited leishmanial hyperpathogenesis, while direct activation of FPRs with WKYMVm enhanced infection and recapitulated the LeishEXO-mediated phenotype." (PMID 39076982, 2024). "The results demonstrated a detrimental impact of Fpr2 on STSLS pathogenesis by restricting the recruitment of neutrophils to the infection site, especially in the early stages of infection." (PMID 36776849, 2023). "The expression of several genes was downregulated following infection, including the chemokine receptor CXCR3 as well as pattern recognition receptors FPR2 and TLR4." (PMID 37138882, 2023). "(B) WT BALB/c mice and AnxA1 KO mice or (C) WT C57BL/6 and FPR2 KO mice were pre-treated with Ac2-26 (i.p; 150 μg) 1 hr before infection with 1 × 106 PFU of DENV-2 via footpad injections (n = 5 for all groups, except for FPR2 KO mock, n = 4)." (PMID 35293862, 2022). "The WT and FPR2-/- mouse survival was similar and elevated throughout the experimental timeline, probably because the C57BL/6 mouse lineage is resistant to infection with T. cruzi." (PMID 34784372, 2021). "Harmful effects of FPR2 have been reported in several respiratory pathologies, such as allergic inflammation, airway contraction, AERD, COPD, and infection." (PMID 33082511, 2020). "We demonstrated a regulatory role of Fpr2 in controlling neutrophil recruitment, which contributes to the pathogenesis of STSLS pathogenesis by decreasing neutrophil recruitment and NETs formation during the early stages of infection." (PMID 36776849, 2023). "Consistent with a chronic inflammatory state, the serum levels of pro-inflammatory cytokines such as TNFα, IFNγ, and IL-1β increased as a result of the infection in the WT and FPR2-/- mice, although the IL-1β increase in the FPR2-/- mice was not significant." (PMID 34784372, 2021). "Although the mRNA levels of IFNγ increased exceedingly upon infection, it was not modified by At-RvD1 or Bz in WT and FPR2-/- mice." (PMID 34784372, 2021). "This indicates that FPR2 may be important for leukocyte recruitment in local infection 27 but has no major impact on systemic infection." (PMID 27470911, 2016). "At early time points, Fpr2-/- mice showed a significant decrease in CXCL1, CXCL2, IL-1β, CCL2, GM-CSF, IL-6, and CCL3 levels at 1 hour and 3 hours after infection, and an increase in IL-22 and IL-23, but there is no change in TNF-α, as compared with WT mice." (PMID 34899755, 2021). "However, the fact that the source of the enterococcal strains from gut or from invasive infection and the level of synergistic hemolysis did not correlate with the capacity to stimulate FPR2/ALX suggests that the enterococcal FPR2/ALX ligands may not contribute much to enterococcal virulence." (PMID 22768166, 2012).
cancer (39 papers, 2013 to 2025). A tumor composed of atypical neoplastic, often pleomorphic cells that invade other tissues. "FPR2 is a multifunctional receptor that is associated with diverse pathophysiological processes, such as inflammation, cancer, amyloidosis, neurodegenerative diseases, wound healing, diabetes and AIDS." (PMID 34930387, 2021). "Recently, experimental evidence suggests that FPR2 is associated with the cancers." (PMID 28600569, 2017). "FPR2 plays important roles in various diseases and is strongly implicated in cancer." (PMID 23549262, 2013). "Further, ligand–receptor interactions differed: never‐smokers exhibited CD27+ B cell interactions via LGALS9–HAVCR2/CD44/CD45 and ANXA1–FPR1/FPR2, whereas smokers utilized CD74‐CXCR4/CD44 pathways linked to cancer progression." (PMID 41377765, 2025). "qRT-PCR results revealed upregulation of SPHK1 and FPR2 in cancer tissues, whereas FCGR2B and VSIG4 were downregulated." (PMID 41150752, 2025). "In epithelial ovarian cancer (EOC), FPR2 significantly promotes cancer cell invasion, migration, and metastasis." (PMID 40330466, 2025). "LL-37 has been reported to activate MAPK via FPR2 in cancer cells, and FPR2 is also suggested to play a role in LL-37-stimulated chemoattraction of white blood cells." (PMID 40063262, 2025). "The results showed that FCGR2B and VSIG4 expression in macrophages was upregulated in cancer samples, while FPR2 expression was downregulated." (PMID 41150752, 2025). "Since cancer cells support their metabolism via glycolysis, we analysed glucose oxidation and proved that FPR2 signalling promoted kinase activity of the bifunctional enzyme PFKFB2 through FGFR1/FRS2- and Akt-dependent phosphorylation." (PMID 37875162, 2023). "In this paper, we provide the first demonstration that FPR2 functionally transactivates IGF-IR in a human cancer cell line." (PMID 37875162, 2023). "Taken together, these results highlight the role of FPR2 in the metabolic reprogramming of cancer cells and suggest FPR2 as a promising therapeutic target for the treatment of human cancers." (PMID 36139766, 2022). "FPR2 is a G-protein coupled receptor that plays a major role in cancer development and inflammation." (PMID 36471379, 2022). "These responses depend on FPR2 activation, being prevented by incubation with the FPR2 antagonist, WRW4, or by a siRNA against FPR2 and suggest a role for FPR2 signaling in cancer cell mitogenesis and invasion." (PMID 23549262, 2013). "IHC assays confirmed increased SPHK1 and FPR2 expression in cancer samples." (PMID 41150752, 2025). "Receptors for eicosanoids in PRN and PRT cancer models are primarily located in immune cells and fibroblasts: Fpr2 is located in granulocytes, Cysltr1 and Ptger4 in macrophages (and B cells in PRT), Ptger3 in fibroblasts, while Ptgir is found in smooth muscle cells." (PMID 37386128, 2023). "However, the role of FPR2 in cancer progression is still controversial and seems related to the nature of its ligands and of cell type, as demonstrated by the observation that LXA4 attenuates pancreatic cell invasion." (PMID 37875162, 2023). "FPR2 contributes to detrimental effects in cancer progression." (PMID 37875162, 2023). "Therefore, FPR2 signalling and Nox2 regulatory subunits are promising therapeutic targets to be explored for the treatment of human cancers." (PMID 37875162, 2023). "Moreover, FPR1 and FPR2 have been shown to play a dual role in the progression/suppression of some types of cancer." (PMID 34148303, 2021). "The highly expressed FPR2 was observed in cancer tissues as well as in metastatic lymph nodes." (PMID 28600569, 2017). "The FPR2 protein was mainly localized in the cytomembrane and cytoplasm of the cancer cells." (PMID 28600569, 2017). "Furthermore, these results could provide new insights into FPR2 signalling as possible drug targets in human diseases, including inflammatory disorders, infections, and cancer, that involve this receptor." (PMID 31784636, 2019).
cancer (continued). "Indeed, previous studies have suggested that human LL-37 is involved in carcinogenesis via multiple reporters, such as FPR2 (FPRL1), epidermal growth factor receptor, and ERBb2, although LL-37 and its fragments and analogs also show anticancer effects in various cancer cell lines." (PMID 26175965, 2015). "Overexpression of FPR2 in EOC cells enhances RhoA expression, leading to increased migratory capacity of the cancer cells." (PMID 40330466, 2025). "The qRT-PCR data revealed significantly higher expression levels of SPHK1 (p < 0.01) and FPR2 (p < 0.05) mRNAs in CRC tissues compared to normal tissues, whereas the expression levels of FCGR2B mRNA were obviously lower in cancer tissues (p < 0.01)." (PMID 41150752, 2025). "This study provides new insights into the molecular mechanisms by which FPR2-induced/TKR signalling and Nox2-dependent ROS generation regulate glucose metabolism in CaLu-6 cancer cells." (PMID 37875162, 2023). "In this study, we mainly concentrated on the upstream mechanism by which RvD1 provided paracrine inhibition of CAFs-derived COMP via FPR2/ROS/FOXM1 cascades to prevent EMT and cancer stemness in HCC." (PMID 30999932, 2019). "Our results indicated that RvD1 impaired paracrine of CAFs-derived COMP by targeting FPR2/ROS/FOXM1 signaling to repress EMT and cancer stemness in HCC." (PMID 30999932, 2019). "Our study provides evidence that ANXA1 modulates TAM function and phenotype through FPR2-ERK signalling, involving CCL5 in the microenvironment, suggesting a potential new axis for targeting cancer therapy." (PMID 29263330, 2017). "A suppression of CD8+ cytotoxic T cells and an expansion of the Tregs population may also be induced by ANXA1 overexpression in TME by FPR2/STAT3 signaling activation, contributing to therapy resistance in several cancer types, including CRC." (PMID 41283264, 2025). "Formyl peptide receptor 2 (FPR2) is a member of the G protein-coupled receptor (GPCR) family, involved in various physiological and pathological processes, including inflammation, immune responses, and cancer progression." (PMID 40330466, 2025). "Moreover, the ALX/FPR2 axis, a main stop signal of inflammation, was shown to be down-regulated in MDA-MB-231 cancer cell lines." (PMID 35045088, 2022). "Interestingly, both cancers showed significant correlations of formyl peptide receptors FPR1 and FPR2 with CSF3 and CSF3R." (PMID 33606788, 2021). "N‐formyl peptide receptors (FPR1, FPR2, and FPR3) play key roles in the regulation of inflammatory processes, and recently, it was demonstrated that FPR1 and FPR2 have a dual role in the progression/suppression of some cancers." (PMID 34148303, 2021). "In this study, we postulated that RvD1 could inhibit COMP secretion in CAFs in a paracrine manner via FPR2/ROS/FOXM1 signaling to block stoma-tumor cells interactions and then suppress EMT and cancer stemness to alleviate malignant progression of HCC." (PMID 30999932, 2019). "ANXA1 binds to macrophages’ FPR2, promoting TAMs polarization towards the immunosuppressive M2 phenotype in TME, by activating the PI3K/AKT and ERK1/2 pathways, leading to tumor progression stimulation by increasing cancer cell resistance to immune-mediated therapies." (PMID 41283264, 2025). "In conclusion, our overall results demonstrate that FPR2 agonists and NOX modulate SLC7A11/xCT expression and activity, thereby identifying a novel regulative pathway of the cystine/glutamate antiport that represents a new potential therapeutical target for the treatment of human cancers." (PMID 38790657, 2024). "In this context, the observation that FPR2 agonists and NOX modulate SLC7A11/xCT expression and activity provides alternative possibilities to control the cystine/glutamate antiport and thus to develop new therapeutical strategies for the treatment of human cancers." (PMID 38790657, 2024).